SIRT1 (sirtuin 1)
Diseases named in the same sentence as SIRT1 in open-access papers (continued):
Sharing a sentence is not in itself a finding about the gene and the disease.
lung carcinoma (continued). "In mesothelioma and lung cancer cells pemetrexed induces ROS generation and SIRT1 function thereby inducing apoptosis." (PMID 31608237, 2019). "Shikonin induced apoptosis of lung cancer cells via activation of Forkhead box O3 (FOXO3a)/early growth response protein 1 (EGR1)/Sirtuin 1 (SIRT1) signaling antagonized by p300." (PMID 30420490, 2018). "The recent meta-analysis spanning 37 selected studies on human solid cancers demonstrates a correlation between higher SIRT1 expression and worse OS in liver and lung cancers." (PMID 30319549, 2018). "The disparity between SIRT1 protein and mRNA levels in lung cancer tissues suggested a post-transcriptional mechanism involved in the regulation of SIRT1." (PMID 29435152, 2018). "SIRT1, a conserved nicotinamide adenine dinucteotide (NAD(+))-dependent deacetylase, has been implicated in the occurrence and development of lung cancer." (PMID 29435152, 2018). "We suggested that SIRT1 was a target of miR-30a, based on both computational predictions and the inverse correlation between miR-30a and SIRT1 levels in human lung cancer tissues." (PMID 29435152, 2018). "Though up-regulation of SIRT1 has been observed in lung cancer, the roles of SIRT1 in the initiation and progression of lung cancer remain poorly understood." (PMID 29435152, 2018). "We further experimentally validated SIRT1 as the direct target of miR-30a by evaluating SIRT1 expression in lung cancer cells after the overexpression or knockdown of miR-30a and by luciferase assay." (PMID 29435152, 2018). "Secondary, although we considered SIRT1 shuttling to be cell-protective, these oxidant-resistant properties might contribute not only to cell survival but also to the malignant transformation of the cell, with resultant lung cancers as an important other CS-associated disease other than COPD." (PMID 29509781, 2018). "Taken together, this study identified a new regulatory axis in which miR-30a and SIRT1 regulate the proliferation, invasion and apoptosis of lung cancer cells and lung tumorigenesis." (PMID 29435152, 2018). "We next analyzed the biological function of miR-30a-driven repression of SIRT1 expression in lung cancer cells." (PMID 29435152, 2018). "Two human lung cancer cell lines (A549 and H1975) was used to further confirm the direct correlation between miR-30a and SIRT1 after overexpression or knockdown of miR-30a." (PMID 29435152, 2018). "Several of the other altered pathways, such as DNA damage repair, rhoGTPase, Wnt/ß-catenin with PKN1 and notch with SIRT1 signaling pathways, are involved in cancerogenesis in general and described in lung cancers." (PMID 29348853, 2017). "Inhibition of SIRT1 induces cell growth arrest, induces apoptosis and enhances chemosensitivity or radiation sensitization in lung cancer cells." (PMID 29312612, 2017). "First, Sirt1 was identified as a biomarker of overall survival in solid malignancies, especially in liver cancer and lung cancer." (PMID 29029516, 2017). "Downregulation SIRT1 expression or inhibition of SIRT1 activation induces apoptosis and enhances radiation sensitization in lung cancer cells." (PMID 29312612, 2017). "Using other lung cancer cell lines, the authors showed that the function of SIRT1 correlates with cell migration." (PMID 27018053, 2016). "Although SIRT1 overexpression reduces p-p38 in cardiomyocytes under ischemia–reperfusion injury, other studies suggest SIRT1 stimulates p-p38 in breast and lung cancer cells as well as in stem cells." (PMID 26824501, 2016).
lung carcinoma (continued). "We show that celecoxib and sulindac inhibit TGF-β1-induced EMT and suppress lung cancer migration and invasion, and that this process involves a SIRT1-mediated signaling pathway." (PMID 27528025, 2016). "In lung cancer, downregulation of SIRT1 by hypoxia in a SUMOylation-dependent fashion facilitated EMT and resulted in cancer metastasis." (PMID 27528025, 2016). "To determine the role of SIRT1 in regulating EMT in lung cancer, we initially screened eight human NSCLC cell lines for baseline expression of SIRT1 and cadherin proteins." (PMID 27528025, 2016). "Taken together, these results indicate that celecoxib and sulindac can inhibit TGF-β1-induced EMT and suppress lung cancer cell migration and invasion via downregulation of SIRT1." (PMID 27528025, 2016). "This is the first study to show that increased expression of SIRT1 performs an important role in TGF-β1-induced EMT in lung cancer." (PMID 27528025, 2016). "Our study demonstrated that SIRT1 was one of the key regulators in B[a]P-induced lung tumorigenesis and would be a potential therapeutic target for lung cancer intervention." (PMID 26318035, 2015). "Changes in proliferation were assessed after SIRT1 and SIRT2 downregulation in lung cancer cell lines using siRNA-mediated technology or tenovin-1, a SIRT1 and SIRT2 inhibitor." (PMID 25915617, 2015). "And the SIRT1 overexpression was also detected in human lung cancer biopsies, both in adenocarcinoma and squamous cell carcinoma." (PMID 26318035, 2015). "The SIRT1 protein expression levels in lung cancer biopsies, both adenocarcinoma and squamous cell carcinoma biopsies, were significantly higher than those in normal ones (p < 0.001)." (PMID 26318035, 2015). "In contrast, SIRT1 activation has been reported to hamper lung cancer metastasis and sensitize NSCLC cells to anticancer drugs." (PMID 25915617, 2015). "Here we support the SIRT1's role in chemoresistance in some types of lung cancer cells and demonstrate that using SIRT1 inhibitor to treat a certain type of lung cancer showing acquired NER capacity would be beneficial for cancer treatment." (PMID 26317794, 2015). "To elucidate the role of SIRT1 in B[a]P-induced lung cancer, we studied the SIRT1 expression and functions in B[a]P-induced BEAS-2B cells, mice lung and patients’ lung biopsies." (PMID 26318035, 2015). "For example, SIRT1 is upregulated in many different cancers, including lymphomas, leukemia and soft tissue sarcomas, prostate cancer, lung cancer, and colon carcinomas." (PMID 25486244, 2014). "In lung cancer, SIRT1 down-regulation by hypoxia in a SUMOylation-dependent manner promotes EMT, and eventually leads to tumor metastasis." (PMID 25424420, 2014). "High level of SIRT1 was found in lung cancer and increased histone methyltransferase G9a, which methylates H3K9 and mono-methylates H3K27, was correlated with poor prognosis." (PMID 24216980, 2013). "The inhibition of endothelial cell growth by DLL4/Notch signaling was enhanced in SIRT1-silenced lung cancer-derived ECs and was rescued by Notch inhibitor DAPT." (PMID 23028940, 2012). "In contrast, activation of SIRT1 signaling through the use of the small molecules SRT1720 or SRT2183 inhibited DLL4-mediated induction of HEY1 and HEY2 expression, indicating that SIRT1 negatively modulated DLL4/Notch1 signaling in lung cancer-derived ECs." (PMID 23028940, 2012). "The cumulative sprout lengths of spheroids in lung cancer-derived ECs transfected with SIRT1 siRNA were significantly shorter than that in the control-transfected cells." (PMID 23028940, 2012). "For example, SIRT1 overexpression has been found in drug-resistant neuroblastoma, osteosarcoma, mammary, ovarian, prostate, colon, and lung cancer cell lines compared with their drug-sensitive counterparts." (PMID 22363646, 2012). "Our results indicated that the SIRT1 protein levels were increased in a time-dependent manner and reached the maximal at 8 h after exposure the lung cancer-derived ECs to hypoxia." (PMID 23028940, 2012).
lung carcinoma (continued). "Inhibition of endothelial cell growth and sprouting angiogenesis by DLL4/Notch signaling was enhanced in SIRT1-silenced lung cancer-derived EC and rescued by Notch inhibitor DAPT." (PMID 23028940, 2012). "However, the underlying mechanism for SIRT1-mediated lung carcinoma angiogenesis remains unknown." (PMID 23028940, 2012). "To further investigate the effects of SIRT1 on the Notch-mediated cell response and tumor growth, we investigated sprout formation in lung cancer-derived ECs and found that inactivation of SIRT1 impaired sprout formation and elongation." (PMID 23028940, 2012). "Lung cancer-derived ECs were isolated from LLC subcutaneous xenografts in endothelial cell-specific SIRT1 knock-in C57BL/6J mice." (PMID 23028940, 2012). "Of the Class III family members Sirtuins (Sirts1-7), Sirt1 has been shown to have altered expression in lung cancer, with 46.4% (45/97) of tumors showing an absence or low expression of SIRT1 protein, which was linked to poor prognosis." (PMID 24212667, 2011). "This evidence deepens our understanding of the tumor-suppressive function of SIRT1 in lung cancer." (PMID 41154674, 2025). "Our findings reveal a novel pathway critical for the regulation of SIRT1 activity in KRASMut lung cancer and provide important evidence for the potential application of SIRT1 activity inhibitors as an adjuvant chemotherapy, overcoming chemoresistance in patients with KRASMut lung cancer." (PMID 40935852, 2025). "Overall, we envisage that targeting SIRT1 ISGylation could amplify the antitumor effects of DNA damage-based therapies in the treatment of lung cancer." (PMID 38443596, 2024). "Importantly, SIRT1 ISGylation promoted lung cancer progression and limited lung cancer cell sensitivity to DNA damage-based therapeutics in vivo and in vitro models." (PMID 38443596, 2024). "The high expression of SIRT1 was related to the longer survival time of patients with lung cancer." (PMID 39403142, 2024). "Accordingly, elevated expression of SIRT1 and ISG15 was associated with poor prognosis in lung cancer patients, a finding that could be translated for lung cancer patient stratification and disease outcome evaluation." (PMID 38443596, 2024). "Elevated ISG15 and SIRT1 levels in lung cancer tissues correlate with poor patient prognosis, suggesting that these biomarkers could aid in patient stratification and outcome evaluation." (PMID 39403142, 2024). "Prompted by our findings that SIRT1 ISGylation is important for tumor progression and the therapeutic response in lung cancer, we analyzed the protein expression levels of SIRT1 and ISG15 in eleven pairs of primary lung adenocarcinoma tissues and adjacent normal tissues." (PMID 38443596, 2024). "In addition, laser confocal microscopy experiments showed that ZMIZ2 and SIRT1 colocalized within the tumor nucleus across various lung cancer cell lines." (PMID 39266996, 2024). "In summary, the miR-9-5p/SIRT1 pathway may be involved the process of smoking-induced lung cancer, which is worth further research to confirm." (PMID 38628672, 2024). "In agreement, in a study of patients with lung cancer, serum SIRT1 levels were lower than those in controls, suggesting that SIRT1 could exert tissue-specific function." (PMID 39766219, 2024). "Therefore, we investigated why SIRT1 K/D is insufficient to exterminate KRASMut lung cancer proliferation." (PMID 37779142, 2023). "Based on these results, SIRT1 inhibitors could be candidate agents for combination therapy for KRASMut lung cancer." (PMID 37779142, 2023). "In the example of the lung cancer cell lines A549 and H1299, it has been shown that programmed death may be preceded by autophagy processes regulated by the SIRT1/AMPK pathway." (PMID 37570691, 2023).
lung carcinoma (continued). "The view that SIRT1 stimulates the survival of cancer cells is additionally supported by the fact that a greater expression of SIRT1 results in higher chemoresistance and lower efficacy of chemotherapy in lung cancer cell line H292." (PMID 37762053, 2023). "Therefore, Sirt1 inhibition in therapeutic combinations with cisplatin or adriamycin reduces chemoresistance in lung cancer cells." (PMID 36011043, 2022). "It is reported that SIRT1 serves as a protumorigenic mediator and targeted SIRT1 activity or gene expression may represent a new strategy for lung cancer and NSCLC therapy." (PMID 34696659, 2022). "Sirt1 confers chemoresistance in lung cancer by deacetylating and stabilizing XRCC1." (PMID 36011043, 2022). "Moreover, overexpression of SIRT1 is a potential therapeutic target for prevention of migration and invasion of lung cancer." (PMID 34696659, 2022). "MiR-30a suppresses lung cancer progression by targeting SIRT1." (PMID 34696659, 2022). "Furthermore, resveratrol increased expression of SIRT1 as well as SIRT1 activator SRT1720-induced autophagy of lung cancer cells." (PMID 35566016, 2022). "The anti-aging gene sirtuin 1 (SIRT1) has been reported to be associated with LUAD and non-small cell lung cancer and high protein level of SIRT1 has been shown to indicate poor prognosis of lung cancer patients 18, 31-33." (PMID 35370463, 2022). "In this study, we investigated whether SIRT1 is involved in TGF-β1-induced EMT during lung cancer cell migration and invasion, and found that its expression increased in TGF-β1-induced NSCLC cells, but Sal treatment inhibited TGF-β1-induced SIRT1 expression." (PMID 33437206, 2021). "Moreover, the findings on SIRT1 in lung cancer cells are indicative of another contrasting field, which is additionally related to melatonin." (PMID 34279445, 2021). "Interestingly, an association between the expression of SIRT1, known to be induced by R, and HMGA1 was highlighted in lung cancer." (PMID 34439473, 2021). "SIRT1 suppression sensitizes lung cancer cells to WEE1 inhibitor-induced DNA damage and apoptosis." (PMID 31956359, 2020). "More importantly, mRNA expression of both Cav-1 and Sirt-1 significantly (p < 0.05) decreased concomitantly with miR204-5p upregulation implying that elevated miR204-5p RNA is associated with TL-induced cytotoxicity in A549 and NCI-H460 lung cancer cells." (PMID 32733649, 2020). "In previous lung cancer studies, SIRT1 has been shown to have oncogenic properties." (PMID 32489467, 2020). "It is known that SIRT1 contributes its effect of tumor promotion to tumorigenesis of lung cancer." (PMID 32467668, 2020). "Notably, ActD also upregulated SIRT1 levels in doxorubicin-resistant lung cancer cell line A549-DXR." (PMID 32151067, 2020). "The SIRT1 inhibitor sirtinol induces senescence-like growth arrest through impaired activation of RAS-mitogen-activated protein kinase (MAPK) signaling in human lung cancer cells." (PMID 31956359, 2020). "Silencing of SIRT1 could significantly enhance the chemosensitivity of lung cancer cells to cisplatin treatment." (PMID 31956359, 2020). "Increased expression of SIRT1 in lung cancer plays a distinct role in Ang II-induced EMT." (PMID 31133857, 2019). "Furthermore, knockdown or inhibitor of APEX1 suppresses migration and invasion and promotes EMT through interaction with sirtuin-1 (SirT1) in non–small cell lung cancer (NSCLC)." (PMID 31454981, 2019). "The class III histone deacetylase silent information regulator 1 (SIRT1) is frequently overexpressed in a variety of tumors, including lung cancer; however, its regulatory mechanisms are largely unknown." (PMID 29435152, 2018). "This suggests that the post-transcriptional regulation of SIRT1 may also be significant in governing SIRT1 expression in lung cancer." (PMID 29435152, 2018).
lung carcinoma (continued). "Importantly, dysregulation of SIRT1 has been demonstrated in various cancers including prostate, breast, ovarian and lung cancers, implicating a pathogenetic role for SIRT1 in malignancies." (PMID 29435152, 2018). "In this study, we found that an inconsistent trend between SIRT1 protein and mRNA levels in human lung cancer tissues, suggesting that a post-transcriptional mechanism may involved in SIRT1 regulation." (PMID 29435152, 2018). "Moreover, we showed that miR-30a inhibited proliferation, invasion and promoted apoptosis of lung cancer cells by inhibiting SIRT1 in vitro and in vivo." (PMID 29435152, 2018). "We next evaluated the effects of miR-30a and SIRT1 on the growth of lung cancer xenograft in mice." (PMID 29435152, 2018). "Moreover, we showed that miR-30a inhibits SIRT1 expression and consequently suppresses proliferation and promotes apoptosis in lung cancer cells." (PMID 29435152, 2018). "We first determined the SIRT1 protein levels in 6 pairs of clinical lung cancer tissues." (PMID 29435152, 2018). "However, the precise role and regulatory mechanism of SIRT1 in the progression of lung cancer remain poorly understood." (PMID 29435152, 2018). "Interestingly, we identified an inconsistent trend between SIRT1 protein and mRNA levels in human lung cancer tissues." (PMID 29435152, 2018). "Interestingly, we found that the restoration of SIRT1 expression successfully attenuates the anti-proliferative and pro-apoptotic effects of miR-30a on lung cancer cells, although miR-30a has many other targets." (PMID 29435152, 2018). "Taken together, our results suggest that SIRT1 is crucial to the proliferation, invasion and apoptosis of lung cancer cells and that miR-30a might suppress proliferation and invasion and promote apoptosis in lung cancer cells by silencing SIRT1." (PMID 29435152, 2018). "We found that SIRT1 protein levels were consistently upregulated in lung cancer tissues." (PMID 29435152, 2018). "Although there is evidence for SIRT1 involving in various cell regulatory and physiological processes, the role of SIRT1 in regulating lung cancer EMT remains unclear." (PMID 27528025, 2016). "Moreover, SIRT1 inhibition enhances the elimination of leukemia stem cells in combination with imatinib and sensitizes natural compound-induced cell death in lung cancer cells." (PMID 26363315, 2015). "Thus, SIRT1 is involved in B[a]P-induced transformation associated with activation of the TNF-α/β-catenin axis and is as a potential therapeutic target for lung cancer." (PMID 26318035, 2015). "To determine the SIRT1 protein levels in human lung cancer tissue, we acquired the lung tissue biopsies from the First Affiliated Hospital of Wenzhou Medical University, including 33 normal biopsies, 36 lung adenocarcinoma and 32 lung squamous cell carcinoma biopsies." (PMID 26318035, 2015). "SIRT1 was overexpressed in the lung of B[a]P-exposed mice and in human lung cancer biopsies." (PMID 26318035, 2015). "In conclusion, SIRT1 could contribute to the development of lung cancer through TNF-α/β-catenin axis." (PMID 26318035, 2015). "Sirt1 was reported to be overexpressed in many cancers, including lung cancer." (PMID 25184156, 2014). "Similarly, tube formation in lung cancer-derived ECs was also repressed when the cells were treated with the SIRT1 deacetylase inhibitor NAM." (PMID 23028940, 2012). "Moreover, treatment with DAPT abrogated the inhibition of the angiogenic response to lung cancer-derived ECs induced through SIRT1 silencing, suggesting that SIRT1 is an important modulator of endothelial angiogenic function." (PMID 23028940, 2012). "We hypothesized that SIRT1 regulation during hypoxia could be conferred via changes in SIRT1 gene expression in lung cancer-derived ECs." (PMID 23028940, 2012). "In our studies, SIRT1 was highly expressed in lung cancer-derived ECs." (PMID 23028940, 2012). "Tubular formation was significantly inhibited in SIRT1-silenced lung cancer-derived ECs." (PMID 23028940, 2012).